MMP2 (matrix metallopeptidase 2)
Diseases named in the same sentence as MMP2 in open-access papers (continued):
Sharing a sentence is not in itself a finding about the gene and the disease.
breast cancer (continued). "The results of Lee at al’s study in a population of Korean women, showed that the single nucleotide polymorphism (SNP) rs143842 of the MMP2 gene was constantly associated with breast cancer prognosis in patients with disease free survival (DFS) or overall survival (OS) events." (PMID 39830522, 2024). "After MLLT11 knockdown, the invasion ability of MDA-MB-231 breast cancer cells was lowered which might be associated with the decreased levels of MMP2 and MMP9 proteins." (PMID 38075552, 2023). "Moreover, high MMP-2 expression in tumor cells was correlated with an increased risk of bone metastasis in breast cancer patients, and MMP-2 overexpression promoted the migration and invasion of breast cancer cells." (PMID 36741729, 2022). "Overall, MMP-2 showed the strongest gene association with breast cancer development." (PMID 34239860, 2021). "Moreover, a higher expression of MMPs was associated with a poorer prognosis in breast cancer patients, with MMP-2 and MMP-9 being the major enzymes involved in this process." (PMID 31514467, 2019). "MMP2 secretion and activation is associated the metastasis of breast carcinoma." (PMID 29734730, 2018). "Furthermore, stromal MMP-2 expression has been closely associated with different clinicopathologic parameters and overall survival of breast cancer patients." (PMID 28545495, 2017). "Alterations of MMP‐2 are often associated with the metastasis of many other cancers, including colorectal cancer, ovarian cancer, and breast cancer." (PMID 28846829, 2017). "Additionally, the expression of functional CD147 and MMP-2 was significantly decreased in Notch1-deficient breast cancer cells which displayed impaired migration and invasion." (PMID 26675551, 2016). "Our findings suggested that MMPs overexpression (especially MMP-9, MMP-2, MMPs overexpression in serum) might indicate a higher risk of poor prognosis in breast cancer." (PMID 26270045, 2015). "MMP1 and MMP2 were associated with survival after diagnosis with breast cancer." (PMID 23696797, 2013). "Only MMP1 and MMP2 were associated with survival after diagnosis with breast cancer." (PMID 23696797, 2013). "Among all women combined, MMP1 and MMP2 were associated with breast cancer risk." (PMID 23696797, 2013). "MT1-MMP enhances focal proteolysis and experimental metastasis, is associated with MMP-2 activation in lung carcinoma and invasive human breast cancer cell lines, and is over-expressed in high-grade gliomas, fibrosarcomas and in carcinomas of the lung, stomach, head and neck." (PMID 19386107, 2009). "Second, MMP-2 levels are increased by overexpression of erbB2; previous studies have shown that erbB2 and Muc1 expression are mutually exclusive in mammary tumors, implying that MMP2 might be part of a transcriptional profile linked to low MUC1 levels." (PMID 16846534, 2006). "Interestingly, PIPP-deficient breast cancer cells exhibit decreased levels of the matrix metalloproteinase MMP2, which digests collagen type IV23, suggesting that PIPP may also regulate extracellular matrix remodeling." (PMID 41408399, 2025). "In addition to breast carcinomas, several other types of cancer, such as oral cancer, retinoblastoma, bladder cancer, and ovarian epithelial cancer, have been associated with MMP2 and MMP9 overexpression." (PMID 40735254, 2025). "Furthermore, rs243842 and rs243867 of the MMP2 gene showed statistically significant associations with a poor breast cancer prognosis regarding DFS, while among OS patients rs243842 in the MMP2 gene and rs4145277 in the HMGB1 gene were significantly associated with poor prognosis." (PMID 39830522, 2024). "In addition, MMP2 is associated with the malignancy and prognosis of breast cancer and lung cancer." (PMID 36172139, 2022).
breast cancer (continued). "Recently, the effect of Fis on MMP-2 and MMP-9 expression in triple breast cancer cells (4T1 and JC cells) was investigated, with the findings that Fis reduced cell motility and that this phenomenon was partially associated with a reduction of MMP-2 and MMP-9 expressions." (PMID 33498927, 2021). "Similarly, Aboussekhra and colleagues demonstrated that SDF-1/MMP-2 secreted by cancer-associated fibroblasts deficient in p16 could induce an EMT in MDA-MB-231 breast cancer cells, again suggesting mechanisms of paracrine regulation of EMT in breast cancer." (PMID 32391382, 2020). "Recent work on breast cancer patients has suggested that MMP-2 negativity may be linked with a favourable prognosis in node-negative breast carcinoma and that high activity levels of plasma MMP-9 in breast cancer patients are associated with a worst overall survival rate." (PMID 15054465, 2004). "For instance, exosomes from metastatic breast cancer cells have been shown to activate MMP‐2, thus remodeling the ECM and inducing the release of specific GFs, resulting in invasion and metastasis." (PMID 40747564, 2026). "For example, exosomes from metastatic breast cancer cells activate MMP‐2, remodeling the ECM and inducing the release of specific GFs, resulting in invasion and metastasis." (PMID 40747564, 2026). "Both ID1 (an MMP2 inhibitor) and MMP2 exhibited a significant decrease in expression in breast cancer cases within the Control group, coupled with greater expression in fibroadenoma samples." (PMID 40806434, 2025). "Mammary tumors that are invasive and have a poor prognosis are related to overexpression of MMP2 or MMP9." (PMID 40735254, 2025). "Our findings align with those in found in HNSCC and breast cancer as it demonstrates that higher KLK-6 expression decreases MMP-2 activity and invasion potential in PCa." (PMID 41509368, 2025). "The ability of MMP-2 to degrade the extracellular matrix of surrounding tissue enhances the migration of cancer cells, thus promoting the invasion of breast cancer cells." (PMID 40176865, 2025). "The clinical validation of these markers is substantial: MMP2 values in tumor tissue have been characterized in basal-like breast cancer patients, demonstrating their role in matrix degradation and invasion." (PMID 41139924, 2025). "This pathway modulation proves critical given the established role of MMP‐2/9 overexpression in facilitating breast cancer metastasis to lung and bone marrow microenvironments via the PKB/PI3K signaling axis activation." (PMID 41234608, 2025). "This study evaluated the relationship between MMP2 (rs2285053) and MMP9 (rs3787268) gene polymorphisms and the susceptibility to breast cancer in Bangladeshi breast cancer patients." (PMID 40735254, 2025). "Targeting matrix metalloproteinase-2 (MMP-2), frequently upregulated in breast cancer stroma, presents an opportunity to enhance tissue-specific drug delivery." (PMID 40732329, 2025). "In the present study, the poor prognosis of MDA-MB-231 and MCF-7 breast cancer cell lines is indicated by the inhibition of MMP2 and MMP9 by RT and/or abemaciclib." (PMID 40035822, 2025). "In breast cancer, AJ ethanol extract can inhibit tumor invasion by inhibiting MMP-2/-9 mRNA expression and upregulating TIMP1/2 mRNA expression." (PMID 39630250, 2025). "Matrix metalloproteinase-2 (MMP-2) has emerged as a critical target in breast cancer due to its elevated expression in the tumor microenvironment." (PMID 40732329, 2025). "Accordingly, our complex network model of HER2-overexpressing breast cancer suggests the therapeutic potential of inhibiting MMP2 and MMP9 as a strategy to target tumours." (PMID 40259907, 2025). "For example, decreased expression of miR-106b leads to increased growth and invasion of breast cancer (BC) cells through increased expression of MMP-2." (PMID 41356146, 2025). "Research findings suggest that FN contribute to the metastasis and invasion of breast cancer by amplifying MMP-2 and MMP-9 levels." (PMID 40940401, 2025).
breast cancer (continued). "While both have been established in breast cancer patients, increased MMP-9 levels are associated with a poor prognosis, while increased MMP-2 levels are linked to prolonged survival time." (PMID 41322296, 2025). "Metabolically reprogrammed CAFs release lactate into the microenvironment, promoting breast cancer cell invasion through the TGF-β1/p38 MAPK/MMP2/-9 signaling axis and enhancing mitochondrial activity." (PMID 40230452, 2025). "We also observed reduced expression of MMP-2 in response to LDHB KO or LDH inhibition in ER- breast cancer cells." (PMID 40507273, 2025). "Both breast cancer cells and CAFs increase the expression and activation of MMP-2 which has a pivotal role in breast cancer progression and relapse." (PMID 41373503, 2025). "In the HER2-negative breast cancer cohort treated with Bevacizumab, MMP2, COL5A2, COL6A1, DLK1, and MDK were identified as predictive of treatment response, aligning with their documented roles in angiogenesis and stromal interactions." (PMID 41139924, 2025). "Network pharmacology studies on potential isolated pathways in cancer target MMP-2 proteins in lung and breast cancer therapy." (PMID 40687624, 2025). "Kaempferol exemplifies multi-targeted efficacy: by downregulating ERK, JNK, and p38 expression, it suppresses MAPK signaling to reduce MMP-2/9 activation, thereby inhibiting adhesion, migration, and invasion in breast cancer MDA-MB-231 cells." (PMID 40620671, 2025). "S100A4 overexpression in breast cancer cells provides increased migratory capacity as the interaction with MMP2 induces EMT." (PMID 39830522, 2024). "Elevated levels of specific MMPs, such as gelatinases MMP-2 and MMP-9, have been found in breast cancer tissues and are associated with a more aggressive tumor phenotype." (PMID 38675538, 2024). "This corroborates with Wang’s findings, wherein Cd exposure induced MMP-2 mRNA expression and consequently fostered the migration and invasion capabilities of human breast cancer cells." (PMID 38535948, 2024). "In the present study, DiMeOC-Mg-BCD was found to inhibit the expression of MMP9 and MMP2 genes in the MDA-MB-231 breast cancer cell line." (PMID 38673967, 2024). "Studies have also shown that SAA reverses paclitaxel resistance in human breast cancer, reduces MMP-2 expression, and inhibits p-ERK protein expression in human nasopharyngeal carcinoma cells and oral squamous cell carcinoma." (PMID 38611749, 2024). "The current analysis further certifies the decisive engrossment of PTGS2/ESR2/EGFR/JUN/MMP2 genes’ signature and some interactor proteins in promoting breast cancer development." (PMID 39707884, 2024). "In cultured breast cancer cells, TNF-α, via the induction of the production of MMP-2 and MMP-9 in tumor-associated macrophages (TAMs), can contribute to the invasion of neoplastic cells into surrounding tissues." (PMID 39339184, 2024). "An inhibitory effect on MMP-2 was observed in all the tested samples in both examined breast cancer cell lines." (PMID 39199694, 2024). "Expressed in lung fibroblasts, MMP-2 has a role in breast cancer progression and enhances tumor cell proliferation in lung metastasis." (PMID 39682261, 2024). "By using LOX-RNAi-LV to transduce the MDA-MB-231 breast cancer cell line, researchers have observed a significant inhibition in the expression of MMP-2 and MMP-9, leading to reduced invasion and migration abilities of breast cancer cells." (PMID 39247609, 2024). "It reduces the production of proteins linked to metastasis, such as MMP-2 and MMP-9, in the MCF-7 breast cancer cell line." (PMID 38672151, 2024). "It has also been described that overexpression of MMP-2 and MMP-9 is associated with poor prognosis in breast cancer patients by promoting the invasive process due to their role in the degradation of ECM proteins." (PMID 38737746, 2024). "MMP-2 and MMP-9 are associated with tumor growth, invasion, angiogenesis, and inflammation in breast cancer." (PMID 38774755, 2024).
breast cancer (continued). "Similar results were obtained when examining the co-expression of PTGS2/ESR2/EGFR/JUN/and MMP2 genes’ signature in breast cancer cell lines representative of different molecular subtypes." (PMID 39707884, 2024). "Les-6287 reduced the concentration of MMP-2, MMP-9, and ICAM-1, all of which are linked to metastasis and a poor prognosis in breast cancer patients." (PMID 39199694, 2024). "According to research on breast cancer, the eHSP complex, which constitutes Hop, HSP40, p23, HSP70, and eHSP90α, is essential for activating MMP2 for breast cancer invasion." (PMID 38994941, 2024). "ARHGDIB can mediate epithelial-mesenchymal transition through the downstream effector MMP-2 as high expression of this gene is indicative of a poor prognosis in breast cancer patients." (PMID 38447798, 2024). "Pro-MMP-2 overexpression enhances the metastatic potential of breast cancer in vivo and significantly increases cell invasiveness in vitro." (PMID 39682261, 2024). "To further dissect the biological contributions of the selected PTGS2/ESR2/EGFR/JUN/and MMP2 genes in breast cancer development, we studied their correlation, as a group, to different breast cancer molecular subtypes and ER / HR status." (PMID 39707884, 2024). "In breast cancer, a relationship between the expression of the Twist factor with MMP-2 and MMP-9 was described and evaluated via immunohistochemistry." (PMID 38542313, 2024). "MFAP5 facilitated the proliferation and metastasis of breast cancer cell, as reflected by the elevated levels of matrix metalloproteinase 2 (MMP2) and MMP9 after MFAP5 overexpression." (PMID 39759103, 2024). "Here, we compared the effects of four polyphenolic compounds on ROS production and on the levels of matrix metalloproteinase (MMP)-2 and -9, which represent important pathogenetic factors of breast cancer." (PMID 38675538, 2024). "It has been reported that during breast cancer invasion and metastasis, the secretion and activation of MMP-2 and MMP-9 increase." (PMID 38737746, 2024). "In breast cancer, increased secretion and activation of MMP-2 and MMP-9 promote tumor cell invasion into other tissues and metastasis to distant organs." (PMID 38737746, 2024). "It is vital to identify the likely biological processes and cellular functions by which PTGS2/ESR2/EGFR/JUN/MMP2 genes’ signature exhibited their tumorigenic effect in breast cancer." (PMID 39707884, 2024). "The dysregulation of the MMP-2 pathway is thought to promote a favorable microenvironment for breast cancer proliferation through the degradation of the extracellular matrix thereby promoting cancer cell migration and invasion." (PMID 39593069, 2024). "Several studies reported the decrease in invasiveness and MMP-2/MMP-9-mediated migration in several breast cancer cell lines, in a cholangiocarcinoma cell line (30 μM) and in a prostate cancer cell line (>5 μM)." (PMID 38540096, 2024). "Differential expression of MMP-2 in breast cancer of varying malignancy grades enabled the identification of different breast cancer subtypes." (PMID 39040452, 2024). "In breast cancer, the overproduction or enhanced activity of MMP-2 leads to the degradation of ECM and BM, enabling tumor cells to invade surrounding tissues and metastasize." (PMID 39451241, 2024). "Overall, both MMP9 and MMP2 have been identified as promising markers for predicting the prognosis of patients with breast cancer." (PMID 39057065, 2024). "Studies have reported that both R-equol and S-equol can inhibit the invasion of human breast cancer MDA-MB-231 cells by downregulating matrix metalloproteinase 2 (MMP-2)." (PMID 38972976, 2024). "Prolonged exposure to cadmium has been demonstrated to enhance the migration and invasion of breast cancer cells through the TGIF/MMP2 signaling axis." (PMID 38807590, 2024).
breast cancer (continued). "After incubation with Les-6287 at 2 μM, the concentration of MMP-2 was lowered to 711.74 pg/mL in the MDA-MB-231 breast cancer cells, in comparison with the control, where the MMP-2 concentration was 1055.21 pg/mL." (PMID 39199694, 2024). "In breast cancer, Lunasin has been shown to suppress the migration and invasion of breast cancer cells by inhibiting matrix metalloproteinase-2/-9 (MMP-2/-9) via the FAK/Akt/ERK and NF-κB signaling pathways." (PMID 38327525, 2024). "It has been demonstrated that overexpression of MMP-2 or MMP-9 led to induction of EMT in breast cancer." (PMID 38539165, 2024). "Breast cancer patients with elevated expression of PTGS2/ESR2/EGFR/JUN/MMP2 genes’ signature displayed significantly poor OS (P = 0.026) and DMFS (P = 0.0066) and consequently unfavorable prognosis." (PMID 39707884, 2024). "In the clinical diagnosis of high-grade (grade-3) breast cancer, the study showed exuberantly increases MMP-2 and MMP-9 mRNA and protein expression." (PMID 36993955, 2023). "For instance, metalloproteases such as MMP-9 or MMP-2 were found to be overexpressed in brain metastases of lung adenocarcinoma cells and breast cancer cells, respectively." (PMID 38072918, 2023). "For instance, in patients with breast cancer, elevated plasma concentration and activity of MMP-2 and -9 have been identified and these biomarkers are associated with an increased risk of disease progression." (PMID 38201092, 2023). "THC treatment decreased the expression level of MMP-9 and MMP-2 in breast cancer cells and increased the expression level of TIMP2." (PMID 36707875, 2023). "Previous studies show that GL-V9 suppresses invasion and migration of human colorectal cancer cells by inhibiting PI3K/AKT and MMP-2/9 signaling, and inhibits the anchorage-independent growth of breast cancer cells." (PMID 37369706, 2023). "MMP2 promotes metastasis in several types of cancer, including gastric cancer, ovarian cancer, breast cancer, and OS." (PMID 37990331, 2023). "This study aims to explore the association between MMP-2, MMP-9, and MMP-11 expression with clinicopathologic features among breast cancer patients in Ethiopia." (PMID 37798646, 2023). "Hypoxia and the HIF-1 pathway have been shown to upregulate several members of the MMP family in breast cancer, including MMP-2 and MMP-9." (PMID 37266453, 2023). "All the treated breast cancer cell lines demonstrated a substantial reduction in MMP-2, MMP-7, and VEGF-A gene expression levels." (PMID 36770598, 2023). "In accordance with our results, it was reported that ALA decreases MMP-2/9 expression in breast cancer cells and vascular smooth muscle cells, thereby reducing cell migration." (PMID 37496822, 2023). "The upregulation of a set of MMPs, including MMP1, MMP2, and MMP9, has been associated with worse prognosis in different malignancies including breast cancer." (PMID 38017545, 2023). "Further, DATS treatment decreased the incidences of breast cancers in xenografted MDA-MB-231 tumor models via reducing MMP-2 and -9 expression levels." (PMID 37021043, 2023). "GABA promotes the invasion of prostate and breast cancer cells through GABABR, and the increasing activities of MMPs, especially MMP‐2 and MMP‐3, are involved in the mechanism underlying this function." (PMID 37199392, 2023). "A plasmonic material with Rh6G as a tag for breast cancer biomarker (MMP-2), along with a standard (2-NT), was used for analyzing the live cells based on the ratio of SERS signals in standard and R6G." (PMID 36979540, 2023).